NEK7 (NIMA related kinase 7)
Diseases named in the same sentence as NEK7 in open-access papers (continued):
Sharing a sentence is not in itself a finding about the gene and the disease.
myocardial ischemia (1 paper, 2024). A disorder of cardiac function caused by insufficient blood flow to the muscle tissue of the heart. "Overall, tilianin suppresses NLRP3 inflammasome activation in myocardial ischemia/reperfusion injury by inhibiting the TLR4/NF-κB and NEK7/NLRP3 pathways." (PMID 39508038, 2024).
Parkinson disease (1 paper, 2024). A progressive degenerative disorder of the central nervous system characterized by loss of dopamine producing neurons in the substantia nigra and the presence of Lewy bodies in the substantia nigra and locus coeruleus. "Regarding miRNAs, currently available data only indicates four bioactive substances with the ability to regulate the miRNAs of NEK7, of which three have been authorized by the FDA, and the other one is a neurotoxin used to modeling Parkinson’s disease." (PMID 38902711, 2024).
renal fibrosis (1 paper, 2025). A final common manifestation of a wide variety of chronic kidney diseases characterized by glomerulosclerosis and tubulointerstitial fibrosis. "The inhibition of NEK7 expression by metformin markedly ameliorated cisplatin-induced serum creatines, tubular injury, renal fibrosis, along with longer survival time and better survival rate." (PMID 40280946, 2025).
sarcopenia (1 paper, 2024). Progressive decline in muscle mass due to aging which results in decreased functional capacity of muscles. "In summary, we present evidence for the involvement of the NLRP3/ASC/NEK7/Caspase-1 inflammasome pathway with activation of pro-inflammatory SASP in the outcome of sarcopenia in the elderly." (PMID 38338718, 2024).
squamous cell carcinoma (1 paper, 2018). A carcinoma arising from squamous epithelial cells. "For example, MMSET promotes cell cycle progression through direct transcriptional upregulation of NEK7, which is a downstream target gene of MMSET in squamous cell carcinomas of the head and neck." (PMID 29796186, 2018).
Stroke (1 paper, 2020). Sudden impairment of blood flow to a part of the brain due to occlusion or rupture of an artery to the brain. "This indicates that NEK7 might activate NLRP3 via activating microtubule acetylation after stroke, which requires further investigation." (PMID 32733353, 2020).
subarachnoid hemorrhage (1 paper, 2020). A serious neurological disorder characterized by intracranial hemorrhage into the subarachnoid space. "The aim of this study was to investigate whether NEK7 is involved in the pathophysiology of subarachnoid hemorrhage." (PMID 32733353, 2020).
ulcerative colitis (1 paper, 2019). An inflammatory bowel disease involving the mucosal surface of the large intestine and rectum. "However, the mRNA expression and protein levels of NEK7 were indeed higher in ulcerative colitis tissues." (PMID 31787755, 2019). "For studying how NEK7 affected the pyroptosis in IBD, we first examined the mRNA expression and protein levels of NEK7, as well as key factors in pyroptosis, including Caspase-1, NLRP3, and GSDMD, in control and ulcerative colitis tissues in IBD patients." (PMID 31787755, 2019). "The mRNA expression of NEK7, Caspase-1, NLRP3, and GSDMD showed to be remarkably increased in ulcerative colitis tissue samples than that in control tissues." (PMID 31787755, 2019).
uterine corpus endometrial carcinoma (1 paper, 2023). A endometrial carcinoma (disease) that involves the body of uterus. "This is further supported by GEPIA data, as uterine corpus endometrial carcinoma has the lowest tumor:normal tissue expression ratios of NEK7 and NEK9." (PMID 37046733, 2023).
cancer (20 papers, 2014 to 2025). A tumor composed of atypical neoplastic, often pleomorphic cells that invade other tissues. "It is recommended to further investigate compound 146476703 at the molecular level, with the goal of synthesizing and developing an effective therapeutic approach for NEK7-related cancers and associated malignancies." (PMID 36922575, 2023). "Like Nek6, Nek7 has been linked to several cancers due to its high levels of expression in them." (PMID 35409400, 2022). "In short, the findings of the current study identify top hits that could prove an effective treatment strategy for NEK7-associated cancer malignancies." (PMID 35807344, 2022). "Over expression of NEK7 leads to the progression of different cancers and associated malignancies." (PMID 35436996, 2022). "NEK7 overexpression has been detected in various human cancers, including GI cancers, where it plays a role in promoting tumor progression." (PMID 40076620, 2025). "NEK7 also modulates oxidative stress pathways, tying it to diseases such as cancer and other inflammatory disorders." (PMID 41154634, 2025). "NEK7 is specifically involved in the regulation of NLRP3 inflammasome activation, which is associated with many diseases including cancer." (PMID 40076620, 2025). "NEK7 has been identified as a significant player in the development of cancer and continues to be a promising target for the development of anticancer drugs." (PMID 36922575, 2023). "As a result, the current study seeks more specific inhibitors that will provide a beneficial treatment option for NEK7-related cancer malignancies." (PMID 35807344, 2022). "A coculture experiment indicated that NEK7-regulated cancer cell pyroptosis inhibited stimulation of HSC activation and tumor-stromal interaction of cancer cells." (PMID 35223495, 2022). "In result, the migration and invasion abilities of cancer cells were significantly decreased after NEK7 knockdown compared to the control group." (PMID 35223495, 2022). "Previous studies reported overexpression of NEK7 in human cancer, including head and neck, breast, pancreas, liver, and colorectum and lung." (PMID 35223495, 2022). "We found that knockdown of NEK7 in cancer cells inhibited the cancer–stromal interaction by repression of cell migratory toward LX-2 cells." (PMID 35223495, 2022). "Knockdown of NEK7 significantly reduced migrated cell numbers and maximum migrated distance of both cancer cells and HSCs." (PMID 35223495, 2022). "We therefore generated cancer organoids for 2 weeks using Luciferase-expressing CFPAC-1 cells transfected with control shRNA or NEK7 shRNA." (PMID 34295827, 2021). "Our results showed that NEK7 was widely detected in PDAC cell lines and associated with the migratory, invasive, proliferation, and adherent capacities of cancer cells." (PMID 34295827, 2021). "In vivo experiments revealed that downregulation of NEK7 expression inhibited cancer cell liver metastases." (PMID 34295827, 2021). "In vivo experiments using a cancer organoid splenic injection model revealed that downregulation of NEK7 inhibited cancer cell liver metastases." (PMID 34295827, 2021). "Our data indicate that NEK7 participates in cancer cell proliferation and is related to the clinical stage as well as pathological grade." (PMID 34419048, 2021). "NEK7 overexpression in HeLa and MDA-MB-231 cells, which have been silenced for the UNC45A gene, restored cell proliferation, showing that NEK7 is a key downstream protein of UNC45A that mediates cell proliferation in cancer cells." (PMID 32294979, 2020). "Eight understudied kinases were found to have hotspot mutations in at least one cancer (CDC42BPA, DYRK1B, DYRK4, LMTK3, MAPK15, NEK7, TSSK1B, and TTBK1), with DYRK4, LMTK3, MAPK15, and NEK7 all having significant hotspot mutations in STAD." (PMID 33205077, 2020).
cancer (continued). "Accordingly, in the last decade, a host of studies have demonstrated the potential role of NEK7 in the cancer development of various tissues." (PMID 33364979, 2020). "Similar to NEK6, NEK7 is also involved in several types of cancer, such as hepatic cancer, squamous cell carcinoma of the head and neck and breast cancer." (PMID 32294979, 2020). "Among them, we again identified three cancer-related genes (NEK7, UBE2D1 and FLRT3), whose mRNA expressions were repressed by miR-101 overexpression in SPAC-1-L cells and induced by AS-101 in HOUA-I cells." (PMID 25153722, 2014). "An emergent target for the development of anti-cancer drugs is NEK7." (PMID 36922575, 2023). "Downregulation of NEK7 suppressed cancer–stromal interaction by inducing cancer cell pyroptosis." (PMID 35223495, 2022). "We next investigated the effect of NEK7 in the cancer–stromal interaction of HCC." (PMID 35223495, 2022). "Our findings suggest that NEK7 plays an important role in cancer–stromal interaction of HCC." (PMID 35223495, 2022). "NEK7 is a promising target for multiple diseases, primarily cancer-related therapy research." (PMID 35807344, 2022). "Moreover, histological analysis revealed that cancer cells that colonized into the liver parenchyma were suppressed in mice injected with NEK7 knockdown cancer cells." (PMID 35223495, 2022). "Nek7 is believed to be a promising biomarker or therapeutic target for treating various cancers." (PMID 35409400, 2022). "The approach of structure-based in-silico drug design was utilized to produce novel inhibitors of the NEK7 protein that may be employed as a powerful and specific therapy option for cancer patients." (PMID 35436996, 2022). "Therefore, downregulation of NEK7 inhibited cancer–stromal interaction by triggering cancer cell pyroptosis." (PMID 35223495, 2022). "In PDAC, the particular mechanism of NEK7 involved in cell adhesion-mediated cancer progression and metastasis remains unclear." (PMID 34295827, 2021). "Differential expression of NEK7 in cancer and adjacent tissues." (PMID 34295827, 2021). "Furthermore, the intimate connection between microtubule instability and unregulated cell division and cancer development suggests that NEK7 has a potential role in oncogenesis." (PMID 33364979, 2020). "Elevated Nek7 levels have been observed in several cancers, and inhibition of Nek7 might provide a route to the development of cancer therapeutics." (PMID 32242624, 2020). "Therefore, NEK7 is a promising target for drug development against various cancer malignancies." (PMID 35807344, 2022). "Therefore, the potential of NEK7-targeted treatment for cancer–stromal interaction of HCC may be possible." (PMID 35223495, 2022). "Moreover, histological analysis using luciferase assay revealed that cancer cell metastatic into liver parenchyma was suppressed in mice injected with NEK7 knockdown cancer organoids, indicating that downregulation of NEK7 in CFPAC-1 organoids suppressed liver metastasis capacity." (PMID 34295827, 2021). "Targeting NEK7 has emerged as a promising therapeutic approach for diseases involving NEK7 dysfunction, such as NLRP3-related diseases and cancers." (PMID 40076620, 2025). "For example, volasertib can cause downregulated BCL2L1 expression, disrupt the interaction between PLK1 and NEK7, or displacement of HMGB2 from mitotic chromosomes, thereby affecting mitotic arrest and apoptosis in cancer cells." (PMID 39872221, 2025). "While most protein kinases have been extensively studied as potential targets for anti-cancer drugs, the NEK kinases have received comparatively limited attention, except for NEK7." (PMID 36922575, 2023). "Taken together, this study highlights the functional role of NEK7-regulated pyroptosis in tumor progression and cancer–stromal interaction of HCC, suggesting NEK7 as a potential target for a new therapeutic strategy of HCC treatment." (PMID 35223495, 2022).
cancer (continued). "Specifically, NEK7 has been suggested to be involved in cell cycle regulation as a member of NIMA-related kinases (NEK) family, and promoting tumor cell proliferation in cancer through relevant mechanisms." (PMID 38902711, 2024). "Given the results of NEK7 and GSDMD in HCC, we speculated that the expression of NEK7 may regulate HCC cell pyroptosis and play a crucial role in cancer progression." (PMID 35223495, 2022). "Moreover, NEK7 inhibited hepatic stellate cell (HSC) activation and cancer–stromal interaction through regulation of cancer cell pyroptosis." (PMID 35223495, 2022). "As knockdown of NEK7 alone was sufficient to induce pyroptosis by mediating GSDMD-N and IL-1β release, these results suggested that NEK7-regulated HCC cell pyroptosis inhibited HSC activation and cancer–stromal interaction." (PMID 35223495, 2022). "Taken together, these results suggest that NEK7-regulated pyroptosis may play an important role in HCC progression; targeting pyroptosis by inhibiting NEK7 could be an effective therapeutic strategy for HCC progression and cancer–stromal interaction." (PMID 35223495, 2022). "We confirmed co-expression of NEK7 and GSDMD in cancer cells of PDAC tissues." (PMID 34295827, 2021). "In the present study, we examined Nek7 expression in HCC cell lines and cancer tissues." (PMID 26921196, 2016).
tumor (15 papers, 2016 to 2025). "Moreover, Nek7 expression associated with tumor numbers, tumor diameter, adjacent organs invasion, tumor grade and TNM stage in HCC patients." (PMID 26921196, 2016). "Taken together, this study proposes Nek7 as a novel tumor associated gene." (PMID 26921196, 2016). "A high level of NEK7 promotes PDAC cell proliferation, migration, and invasion and is associated with advanced tumor stages, liver metastasis, and poor prognosis." (PMID 40076620, 2025). "Knockdown of NIMA-related kinase 7 (NEK7) activates the NLRP3/caspase-1/GSDMD axis to inhibit tumor progression." (PMID 40806716, 2025). "Silencing NEK7 confirmed its role in promoting GC tumor growth both in vitro and in vivo xenograft models." (PMID 40076620, 2025). "To explore the plausibility of these gene as carcinogenic factors, we conducted an extensive literature retrieval and found several studies providing evidence supported the association between NEK7 and LHX9 with tumor initiation and progression." (PMID 38902711, 2024). "Five drugs and two molecules targeting NEK6 and NEK7 have already exhibited anti-tumor effects in investigations or clinical trials." (PMID 38902711, 2024). "NEK7 expression in four tumour cell lines was significantly down-regulated while ZW10 were upregulated, regardless of protein and mRNA levels." (PMID 38365687, 2024). "Taken together, these results indicated that downregulation of NEK7 reduced the colonization and proliferation of HCCs and inhibited tumor formation in vivo." (PMID 35223495, 2022). "In vivo experiments using a splenic injection model revealed that downregulation of NEK7 inhibited HCC tumor formation." (PMID 35223495, 2022). "In a splenic xenograft mouse model, knockdown of NEK7 expression suppressed HCC primary tumor formation." (PMID 35223495, 2022). "Meanwhile, decreased expression of Ki67 and p-ERK1/2 indicates that knockdown of NEK7 suppressed the tumor formation capacity of HCCs." (PMID 35223495, 2022). "Cell viability, migration, and invasion capacity of HCC cell lines were inhibited, and the tumor growth in the xenograft mouse model was also suppressed following knockdown of NEK7 expression." (PMID 35223495, 2022). "In the present study, by using bioinformatic databases, cell lines, and tumor samples, we investigated the correlation between NEK7 expression and GSDMD expression in human HCC." (PMID 35223495, 2022). "In the present study, we examined a NEK7 expression pattern with GSDMD in l HCC and investigated the functional impact of NEK7-regulated pyroptosis on tumor progression." (PMID 35223495, 2022). "By using fresh frozen samples of tumor and paired tumor-adjacent normal tissues from our institution, we found that NEK7 and GSDMD were significantly upregulated in tumor tissues compared to normal tissues." (PMID 35223495, 2022). "We investigated the protein expression level of NEK7 in tumor tissues and adjacent normal tissues using immunohistochemistry of 90 patients with PADC." (PMID 34295827, 2021). "NEK7 exerts a regulatory effect on cell proliferation and is closely related to tumor immune infiltration." (PMID 34419048, 2021). "High expression level of Nek7 was significantly correlated with tumor numbers, tumor diameter, adjacent organs invasion, tumor grade and TNM stage." (PMID 26921196, 2016). "In HCC patients, high Nek7 expression was significantly correlated with tumor numbers, tumor diameter, adjacent organs invasion, tumor grade and TNM stage." (PMID 26921196, 2016). "Taken together, these results suggest that NEK7 might contribute tumor progression and prognosis of PDAC." (PMID 34295827, 2021). "Moreover, we confirmed that expression of NEK7 was significantly increased in tumor tissues than tumor-adjacent normal tissues in patients with PDAC (P = 0.0252)." (PMID 34295827, 2021). "Furthermore, in vivo experiment demonstrated that the tumor growth in xenograft mice with Nek7/knock-down SMMC7721 cells was obviously suppressed." (PMID 26921196, 2016).
tumor (continued). "Therefore, SHCBP1 may maintain the functions of tumour cell centrosomes and spindles by regulating NEK7 expression." (PMID 38365687, 2024). "Moreover, the isolated tumor tissues were subjected to IHC staining for Nek7 and Ki-67." (PMID 26921196, 2016). "Nonetheless, the KMPlot data suggest potential avenues for exploring the tumor-suppressive qualities of NEK6, NEK7, and NEK9 in kidney renal cell carcinoma." (PMID 37046733, 2023). "Generally, EAC tissues expressed significantly higher NEK3 and NEK9 as compared to normal esophageal epithelial cells, predominantly located in cytosol in both normal and tumor cells for NEK3 and NEK7." (PMID 37835513, 2023). "Previous studies showed overexpression of NEK7 and NEK6 in a series of human tumor types, and the biological roles of NEK6 and NEK7 were extremely similar in cell cycle and cell proliferation enhancement." (PMID 34295827, 2021). "By Nek7 silencing using lentivirus-mediated Nek7 interference approach, the growth of HCC cell lines was inhibited and the tumor growth in xenograft mouse model was also suppressed." (PMID 26921196, 2016). "To address this, we used lentivirus-mediated specific shRNA targeting Nek7 to investigate the impact of Nek7 silencing on the HCC cell proliferation and SMMC7721 xenograft tumor growth." (PMID 26921196, 2016). "Evidence suggesting that the expression of NEK7 and LHX9 may be potential reasons for the inverse correlation between Treg cells and CRC risks, whereas the factors for the anti-tumor effects of DN cells remains uncertain." (PMID 38902711, 2024). "We observed NEK7 expression was upregulated in tumor tissues compared to normal tissues at both RNA and protein levels using bioinformatic analysis and immunohistochemistry analysis in PDAC." (PMID 34295827, 2021). "To further explore the role of NEK7, we conducted Gene Set Enrichment Analysis (GSEA) between low and high NEK7 expression samples, we found significant differences (p < 0.05) in enrichment of cell adherent, cell fate, and tumor microenvironment pathways in KEGG and Biological process." (PMID 34295827, 2021). "By contrast, NEK1, NEK7, and NEK9 expression showed no obvious trend with the tumour grade." (PMID 38706902, 2024).